FCGR2B (Fc gamma receptor IIb)
Diseases named in the same sentence as FCGR2B in open-access papers (continued):
Sharing a sentence is not in itself a finding about the gene and the disease.
glomerulonephritis (14 papers, 2012 to 2025). A renal disorder characterized by damage in the glomeruli. "Both ISD017 and cyclophosphamide treatment increased long-term survival and reduced the severity of glomerulonephritis in Fcgr2b-deficient mice." (PMID 38745067, 2024). "In summary, ISD017 treatment in symptomatic 129.B6.Fcgr2b-deficient mice reduced the severity of glomerulonephritis and increased long-term survival." (PMID 38745067, 2024). "Notably, the targeted STING inhibitor ISD017 has shown effectiveness in reducing glomerulonephritis in Fcgr2b-deficient mice, as well as diminishing ISG responses in peripheral blood mononuclear cells (PBMC) from SLE patients." (PMID 38886451, 2024). "By using Fcgr2b-/- mice that were also deficient in Act1, a crucial adaptor molecule downstream from the IL-17RA/IL-17RC complex, it was shown that IL-17A deletion significantly reduced inflammatory monocyte and neutrophil infiltration and thus the severity of glomerulonephritis." (PMID 32059488, 2020). "The data suggested that ISD017 and CYC preferentially inhibited interferon-inducible genes in the kidney, which lessened glomerulonephritis in Fcgr2b−/− mice." (PMID 38745067, 2024). "Furthermore, it is noteworthy that Fcgr2b−/− mice develop fatal glomerulonephritis that is dependent on IL-17 signaling, while renal Th17 cells are also observed in ANCA-associated glomerulonephritis in humans." (PMID 32541026, 2020).
viral infection (11 papers, 2017 to 2025). "Similar to FCGR2B, genetic variants in the FCGR3A gene have been associated with SLE47, as well as immunodeficiency, susceptibility to recurrent viral infections, and alloimmune neonatal neutropenia." (PMID 39990346, 2025). "Following viral infection, a significant increase in the frequency of microglia expressing iNOS was found in FcgR2b KO mice (8.07%) when compared with either WT (3.68%) (***p < 0.001) or Fcer1g KO mice (3.08%) (***p < 0.001) at 14 dpi." (PMID 28165503, 2017).
COVID-19 (10 papers, 2020 to 2025). A disease caused by infection with severe acute respiratory syndrome coronavirus 2. "BCR inhibitory gene expression was limited, but CD22 was detectable across B cell subsets in asymptomatic COVID-19, while FCGR2B, CD72 and PTPN6 expression was evident in B cells in severe COVID-19." (PMID 33879890, 2021).
immune thrombocytopenia (9 papers, 2012 to 2024). "One study on children with idiopathic thrombocytopenia (ITP) also showed a similar pattern, that the FCGR2B 232I/T was less frequently detected in acute ITP in comparison with chronic ITP." (PMID 22879986, 2012).
glioma (8 papers, 2016 to 2025). A benign or malignant brain and spinal cord tumor that arises from glial cells (astrocytes, oligodendrocytes, ependymal cells). "For example, studies have shown that expression of FCGR2B and SIGLEC10 in gliomas was higher than in normal tissue where it was associated with a poor prognosis." (PMID 40894037, 2025). "Therefore, based on our findings, FCGR2B could be a target for immune checkpoint inhibition to improve antitumor response of immunotherapy for glioma patients." (PMID 27738332, 2016). "To further explore the role of MHC in gliomas, we used LASSO regression analysis and identified four genes (TNFSF14, MXRA5, FCGR2B, and TNFRSF9) related to the major histocompatibility complex (MHC)." (PMID 40429753, 2025). "Using WGCNA and LASSO algorithms, we identified four MHC-related genes (TNFSF14, MXRA5, FCGR2B, and TNFRSF9) as prognostic biomarkers for glioma." (PMID 40429753, 2025). "Most of which (6/7, no data for FCGR2B in this study) we confirmed were differentially expressed between different grades of gliomas." (PMID 28291232, 2017). "First, through the Brain Tumor Immune Micro Environment (Brain TIME) analysis, we found that FCGR2B in microglia and infiltrating monocyte-derived macrophages (MDMs) was more highly expressed in IDH wild-type (IDH_WT) glioma tissues or brain metastases (BrMs) than in non-tumor tissues." (PMID 36685974, 2022). "Among the 10 candidates, high mRNA expression of CCL8, FCGR2B, and TUBA4A and low mRNA expression of GABRD, PRAME, and SYN1 were significantly correlated with worse prognosis, while the mRNA expression of CCL18, SCN1B, SNCB, and VSNL1 showed no connection to the overall survival of glioma patients." (PMID 36685974, 2022).
liver fibrosis (8 papers, 2019 to 2024). "Reduced FcγRIIb expression is reported in damaged LSECs in chronic liver inflammation and cirrhosis, and single-cell RNA sequencing of liver of mice with CCl4 induced liver fibrosis showed loss of Fcgr2b in the pericentral zone of the hepatic lobule, i.e. in the zone with most severe pathology." (PMID 37910485, 2023). "Arsenic-suppressed H3K18ac could trigger the dedifferentiation of LSECs via the inhibiting transcriptional activation of Fcgr2b and Lyve1, which are key genes responsible for maintaining the differentiation phenotype of LSECs, thereby promoting liver fibrosis." (PMID 37999580, 2023). "In contrast to LyECs, Mcam, Fcgr2b (CD32b), Cxcl9, CD36, Kit, Clec4g, etc., genes were highly expressed in LSECs from CCl4-induced liver fibrosis, NASH and BDL mice." (PMID 36632228, 2023). "The expression of Fcgr2b and Spp1 was increased only in aggravated fatty liver, and the expression levels of Cxcl2 and Elane increased when liver fibrosis occurred which is not completely reversible, suggesting that these genes may play a key role in the prognosis of NAFLD." (PMID 36426356, 2022).
nephritis (8 papers, 2007 to 2024). Inflammation of renal tissue. "In comparison, we analyzed nephritis development in female Fcgr2b−/− mice that expressed one “knock-in” allele of the self- and polyreactive 56R VDJ4 Ig heavy chain (haplotype a) (56R+/−Fcgr2b−/− mice)." (PMID 29928274, 2018). "IL-1β is a potent proinflammatory cytokine that has previously been identified in glomerular macrophages in diseased MRL-lpr mice as well as Fcgr2b−/− mice, while elevated renal IL-1 family cytokine responses are common to several models of nephritis." (PMID 32541026, 2020). "The ICs were then transferred to Fcgr2b−/− mice and, 2 weeks later, the nephritis was induced by injecting TNP-sheep IgG Abs in CFA followed by i.v. injection of sheep anti-GBM NTS 4 days later." (PMID 29928274, 2018). "In contrast, the ICs containing native sialylated polyreactive IgG Abs attenuated nephritis-induced mortality in Fcgr2b-/- mice." (PMID 29928274, 2018). "The Fcgr2b−/−.Stinggt/gt mice did not develop overt kidney inflammation; thus, it is likely to release less amount of oxidized mtDNA." (PMID 33083760, 2020). "Fcgr2b−/− mice positive for IgG autoAbs started to develop proteinuria by the age of 6 months, and about a half of the Fcgr2b−/− mice died due to severe nephritis by the age of 9 months (B and data not shown)." (PMID 29928274, 2018).
periodontitis (8 papers, 2010 to 2025). An acute or chronic inflammatory process that affects the tissues that surround and support the teeth. "In the present study, by performing multiple bioinformatics analysis methods, we firstly identified six key OS-genes (CXCR4, SELL, FCGR3B, FCGR2B, PECAM1, and ITGAL) in periodontitis, whose expression levels were significantly upregulated." (PMID 36148415, 2022). "Six of them were identified as key OS-genes (CXCR4, SELL, FCGR3B, FCGR2B, PECAM1, and ITGAL) in periodontitis." (PMID 36148415, 2022).
glioblastoma (7 papers, 2019 to 2023). The most malignant astrocytic tumor (WHO grade IV). "A profound biomarker utility of FCGR2B has been quite recently shown in patients with recurrent glioblastoma, in whom increased expression was correlated with decreased OS." (PMID 37509358, 2023). "FCGR2B, an inhibitory Fcgamma receptor, has been proven to be a prognostic factor for patients with glioblastoma." (PMID 33845841, 2021). "Through analyzing patients’ clinical information and genetic profiles from online databases, TIMP1, ITGA5, FCGR2B, UPP1, ISG20, TSPAN4, and LOXL1 were identified as potential prognostic biomarkers for glioblastoma." (PMID 35778451, 2022). "We found that TIMP1, ITGA5, FCGR2B, UPP1, ISG20, TSPAN4, and LOXL1 are potential biomarkers correlated with the immune infiltration events in patients with glioblastoma." (PMID 35778451, 2022). "In addition, we used the SurvExpress analysis to further assess the prognostic value of TIMP1, ITGA5, FCGR2B, UPP1, ISG20, TSPAN4, and LOXL1 using other glioblastoma patient cohorts, including TCGA Glioblastoma and GSE4412." (PMID 35778451, 2022). "Although the relationship between FCGR2B and prognosis in sarcoma patients had not been reported, the prognostic value of FCGR2B had been widely confirmed in other cancers, such as hepatocellular carcinoma and glioblastoma." (PMID 32854645, 2020).
Obesity (7 papers, 2018 to 2025). Accumulation of substantial excess body fat. "Fc-gamma receptor-IIb (FcγRIIb) and its ligand are reported to be associated with obesity and type 2 diabetes mellitus (T2DM)." (PMID 30261661, 2018).
breast carcinoma (6 papers, 2016 to 2024). "Based on the TCGA breast cancer microarray data alone, it is not clear if the detected expression of FCGR1A and FCGR2B is actually localised exclusively in the macrophages." (PMID 27876705, 2016).
diabetes (6 papers, 2018 to 2025). "The area under the curve (AUC) values for S100A12, IL1R1, and FCGR2B were 0.744, 0.785, and 0.868, respectively, indicating robust diagnostic efficacy for diabetes-associated IDD." (PMID 41169383, 2025). "FCGR2B knockdown alleviates diabetes-induced cognitive dysfunction by altering neuronal excitability in the hippocampus." (PMID 40537751, 2025). "Second, compared to ALB, which primarily serves as a blood glucose indicator, and AREG, which lacks sufficient evidence linking it to cognitive function, FCGR2B has a well-established mechanistic connection to both cognitive impairment and diabetes." (PMID 40537751, 2025). "Our study mined multiple gene expression profiles from hippocampus of DM mice, and identified Fc gamma receptor 2b (FCGR2B) as a potential diabetes-induced cognitive dysfunction driver." (PMID 40537751, 2025). "The main text is on the role of FCGR2B on diabetes-induced cognitive dysfunction." (PMID 40537751, 2025). "To elucidate the regulatory role of FCGR2B in this process, we conducted a series of experiments demonstrating that FCGR2B knockdown not only ameliorated diabetes-induced reduction of dendritic spine density in hippocampal neurons but also increased NeuN-positive cell numbers." (PMID 40537751, 2025).
atherosclerosis (5 papers, 2016 to 2023). A disease characterized by the build-up of fatty material and calcium deposition in the arterial wall resulting in partial or complete occlusion of the arterial lumen. "In contrast to several previous studies that reported enhanced atherosclerosis, Harmon et al19 found decreased atherosclerosis in Fcgr2b−/−Apoe−/− mice." (PMID 31092015, 2019).
Alzheimer disease (4 papers, 2016 to 2025). A progressive, neurodegenerative disease characterized by loss of function and death of nerve cells in several areas of the brain leading to loss of cognitive function such as memory and language. "Specifically, silencing FCGR2B has been shown to prevent the accumulation of oligomeric β-amyloid 1–42 (Aβ1–42) in neurons of Alzheimer’s disease mice." (PMID 40537751, 2025). "Unlike samples taken from people without Alzheimer’s disease, neurons in these samples contain both phosphorylated Fc gamma receptor IIb and hyperphosphorylated tau proteins." (PMID 27834631, 2016).
Sepsis (4 papers, 2014 to 2020). Sepsis is defined as life-threatening organ dysfunction caused by a dysregulated host response to infection. "FCGR2B deficient mice have been shown to have increased bacterial clearance and survival in sepsis." (PMID 24612859, 2014).
follicular lymphoma (3 papers, 2019 to 2023). Follicular lymphoma is a form of non-Hodgkin lymphoma characterized by a proliferation of B cells whose nodular structure of follicular architecture is preserved. "Expression of FCGR2B has been shown to decrease the response rate to rituximab monotherapy in follicular lymphoma." (PMID 36671500, 2023).
Graves disease (3 papers, 2020 to 2025). Graves' disease is an autoimmune disorder that leads to overactivity of the thyroid gland (hyperthyroidism).It is caused by an abnormal immune system response that causes the thyroid gland to produce too much thyroid hormones. "Reduced FCGR2B gene expression has also been observed in the PBMCs of patients with active Graves’ disease." (PMID 33424774, 2020).
hepatocellular carcinoma (3 papers, 2020 to 2025). A malignant tumor that arises from hepatocytes. "Our MR analysis further confirmed the potential pathogenic role of FCGR2B in liver cancer, revealing its possible mechanism as an immune regulatory factor in the pathogenesis of hepatocellular carcinoma." (PMID 40376263, 2025).
memory impairment (3 papers, 2016 to 2025). "Recently, we showed that Fc gamma receptor IIb (FcγRIIb) is also expressed in neurons and directly interacts with Aβ1-42 to mediate Aβ neurotoxicity, synaptic dysfunction, and memory impairment in AD pathogenesis." (PMID 27834631, 2016). "Previous study has confirmed that FCGR2B is upregulated in hippocampal neurons of AD patients, and regulated Aβ induced neurotoxicity and memory impairment It suggests that FCGR2B may be involved in neuronal damage and cognitive dysfunction." (PMID 40537751, 2025). "FCGR2B (Fc gamma receptor IIb) mediates Aβ neurotoxicity and memory impairment in AD." (PMID 36005139, 2022).
metastatic melanoma (3 papers, 2010 to 2025). A melanoma that has spread from its primary site to another anatomic site. "Other studies have identified FCGR2B as a marker of human metastatic melanoma, where its expression impairs the tumor susceptibility to FcgammaR-dependent innate effector responses." (PMID 40697816, 2025).
preeclampsia (3 papers, 2022 to 2025). Preeclampsia is a hypertensive disorder of pregnancy that is characterized by new-onset hypertension with proteinuria presenting after 20 weeks of gestation, and depending on mild or severe forms may initially present with severe headache, visual disturbances, and hyperreflexia. "In our study, several novel predictive biomarkers were associated with late-onset preeclampsia, including IDUA, FCGR2B, and CD4." (PMID 38253981, 2024).
schizophrenia (3 papers, 2020 to 2022). A major psychotic disorder characterized by abnormalities in the perception or expression of reality. "Yet the inhibitory receptor, FcGR2B, was unchanged, suggesting a more volatile antibody-driven response in some individuals with schizophrenia." (PMID 35841099, 2022). "Gene transcript levels of FcGRT, FcGR3A, and FcGR2B were detected in the midbrain of both schizophrenia cases and control subjects." (PMID 35841099, 2022). "In contrast, FcGRT and FcGR3A mRNA levels were elevated in the midbrain from “high inflammation” schizophrenia cases (FcGRT; p = 0.02, FcGR3A; p < 0.0001) in comparison to low-inflammation patients and healthy controls, while FcGR2B mRNA levels were unchanged." (PMID 35841099, 2022). "In contrast, the mRNA levels of the anti-inflammatory receptor FcGR2B were unchanged when comparing schizophrenia cases and control subjects, regardless of the inflammatory biotype of schizophrenia cases." (PMID 35841099, 2022). "The absence of concurrent FcGR2B up-regulation in the subset of high-inflammation schizophrenia patients suggests an inability to terminate immune complex-Fcγ receptor-mediated processes." (PMID 35841099, 2022). "Levels of FcGR2B mRNA have not been determined in the brains of people with schizophrenia." (PMID 35841099, 2022).
Splenomegaly (3 papers, 2017 to 2021). Abnormal increased size of the spleen. "In Fcgr2b−/− mice, the development of IgG2a and IgG2b autoAbs was associated with splenomegaly, increased frequencies of Th1 and PCs and IC accumulation in the kidneys." (PMID 29928274, 2018).
Stroke (3 papers, 2012 to 2022). Sudden impairment of blood flow to a part of the brain due to occlusion or rupture of an artery to the brain. "At 8 weeks post-stroke, the top 10 genes were Cd44 (degree = 14), Fcgr2b (degree = 13), C1qb (degree = 13), Cd74 (degree = 12), C1qc (degree = 11), Cd14 (degree = 10), C4a (degree = 10), Spp1 (degree = 10), RT1-A2 (degree = 9), and Itgb2 (degree = 9)." (PMID 31888302, 2019). "Of these, Fcgr2b, Fcgr3a, and Tnfrsf26 also displayed a strong age effect, being more strongly upregulated early after stroke in aged (2- to 3-fold) than in young rats." (PMID 23251410, 2012). "Aged rats, on the contrary, had early post-stroke increases in expression of phagocytosis-promoting genes like Fcgr2b and Fcgr3a, and for the pro-apoptotic acting gene, tumor necrosis factor receptor superfamily, member 26 (Tnfrsf26)." (PMID 23251410, 2012). "At 4 weeks post-stroke, the top 10 gene products in the PPI network were Cd44 (degree = 17), C1qb (degree = 15), Fcgr2b (degree = 14), Spp1 (degree = 12), Cd74 (degree = 12), C4a (degree = 12), C1qa (degree = 12), C3 (degree = 10), Cd14 (degree = 10), and Itgb2 (degree = 10)." (PMID 31888302, 2019).
carcinoma of the uterine cervix (2 papers, 2012 to 2020). "For example, Bevacizumab and cetuximab has been reported to target FCGR1A and FCGR2B, and these 2 drugs have already been approved for clinical treatment of cervical cancer." (PMID 32733542, 2020).
Cognitive impairment (2 papers, 2016 to 2025). Abnormal cognition is characterized by deficits in thinking, reasoning, or remembering. "In addition, the expression of ALB, AREG and FCGR2B was notably elevated in hippocampus of DM mice, showing that these proteins may be closely associated with cognition impairment of DM mice." (PMID 40537751, 2025). "To further assess FCGR2B silencing on DM-induced cognition impairment, we tested the body weight, the FBG and the insulin level." (PMID 40537751, 2025). "Our results demonstrate that, apart from AD and diabetic retinopathy, we have demonstrated previously that the FCGR2B is highly expressed in DM cognitive impairments mice." (PMID 40537751, 2025). "And another one of our findings that FCGR2B knockdown might alleviated the cognitive impairments observed in DM cognitive impairments mice." (PMID 40537751, 2025). "Next, the impact of FCGR2B on DM-induced cognition impairment was detected in vivo." (PMID 40537751, 2025). "All these data indicated that FCGR2B may be closely related to DM-induced cognition impairment." (PMID 40537751, 2025).
colitis (2 papers, 2019 to 2021). Inflammation of the colon. "Here we show increased expression of FcγRIIB (human FCGR2B)—which encodes an inhibitory receptor—by tuft cells in a mouse model of colitis, suggesting another possible involvement for this pathway in inflammatory bowel disease through tuft cells." (PMID 34497389, 2021). "Little change in colonic B cells was observed after IL-1β blockade in Fcgr2b−/− mice; however, there was a reduction in the severity of colitis and colonic neutrophil infiltration, directly implicating this pathway in detrimental immune responses driven by dysregulated FcγR signaling." (PMID 30876876, 2019).
immune deficiencies (2 papers, 2022 to 2025). "Six genes related to (a) immune checkpoints (n = 2; BTLA and CD6); (b) regulatory macrophages and T cells (n = 2; CCR7 and CD3D); and (c) immune deficiencies and unfavorable prognosis (n = 2; CD3E and FCGR2B) were down-regulated post-RT compared with pre-RT (statistical p-range: <0.0001–0.0415)." (PMID 36291815, 2022).